MIR6746 (microRNA 6746)
Synonyms: hsa-mir-6746
Gene: MicroRNA gene on chromosome 11 (61,878,216 to 61,878,278, reverse strand). Ensembl gene ENSG00000277892.
Homologues: Orthologues: chimpanzee MIR6746 (100% identical).